PTPN11 (protein tyrosine phosphatase non-receptor type 11)
Description:
Acts downstream of various receptor and cytoplasmic protein tyrosine kinases to participate in the signal transduction from the cell surface to the nucleus. Positively regulates MAPK signal transduction pathway. Dephosphorylates GAB1, ARHGAP35 and EGFR. Dephosphorylates ROCK2 at 'Tyr-722' resulting in stimulation of its RhoA binding activity. Dephosphorylates CDC73. Dephosphorylates SOX9 on tyrosine residues, leading to inactivate SOX9 and promote ossification (By similarity). Dephosphorylates tyrosine-phosphorylated NEDD9/CAS-L. Acts as an effector of PDCD1-mediated inhibition of T-cell response: recruited by phosphorylated PDCD1, mediating dephosphorylation of key T-cell receptor (TCR) proximal signaling molecules, leading to TCR signaling inhibition.
Synonyms: PTP-1D; SHP-2; Shp2; PTP2C; BPTP3; SH-PTP2; CFC; JMML; METCDS; NS1; SH-PTP3
Tractability: Small molecule: a drug acting on it is in phase 2 or 3 trials; a structure with a bound ligand is known; a high-quality ligand is known; it belongs to a druggable protein family. PROTAC: it is named in the literature on targeted protein degradation; ubiquitination databases record sites on it; its protein half-life has been measured; a small molecule that binds it is known.
Target class: Tyrosine protein phosphatase; Enzyme; Phosphatase; Protein Phosphatase
Chemical probes: Batoprotafib (high quality)
Gene: Protein-coding gene on chromosome 12 (112,418,351 to 112,509,918, forward strand). Ensembl gene ENSG00000179295.
Subcellular location: Cytoplasm; Nucleus
Subcellular location (Human Protein Atlas): Nucleoli rim; Actin filaments; Cytosol; Nucleoplasm
Pathways (Reactome):
Signal Transduction: Activated NTRK2 signals through FRS2 and FRS3; Downstream signal transduction; FRS-mediated FGFR1 signaling; FRS-mediated FGFR2 signaling; FRS-mediated FGFR3 signaling; FRS-mediated FGFR4 signaling; GAB1 signalosome; MAPK1 (ERK2) activation; MAPK3 (ERK1) activation; MET activates PTPN11; Negative regulation of FGFR1 signaling; Negative regulation of FGFR2 signaling; Negative regulation of FGFR3 signaling; Negative regulation of FGFR4 signaling; PI-3K cascade:FGFR1; PI-3K cascade:FGFR2; PI-3K cascade:FGFR3; PI-3K cascade:FGFR4; PI3K Cascade; PI5P, PP2A and IER3 Regulate PI3K/AKT Signaling; PIP3 activates AKT signaling; Signaling by Leptin; Signaling by SCF-KIT; Spry regulation of FGF signaling
Immune System: Activation of IRF3, IRF7 mediated by TBK1, IKKε (IKBKE); Co-inhibition by BTLA; Co-inhibition by CTLA4; Co-inhibition by PD-1; FLT3 Signaling; Interferon alpha/beta signaling; Interleukin-20 family signaling; Interleukin-3, Interleukin-5 and GM-CSF signaling; Interleukin-37 signaling; Interleukin-6 signaling; Prolactin receptor signaling; Regulation of IFNA/IFNB signaling; Regulation of IFNG signaling; STAT5 Activation; Signaling by CSF1 (M-CSF) in myeloid cells; Signaling by CSF3 (G-CSF)
and 12 more pathways
Gene Ontology:
Molecular function: cadherin binding; cell adhesion molecule binding; insulin receptor binding; molecular adaptor activity; non-membrane spanning protein tyrosine phosphatase activity; phosphoprotein phosphatase activity; phosphotyrosine residue binding; protein binding; protein tyrosine kinase binding; protein tyrosine phosphatase activity; signaling receptor complex adaptor activity; protein kinase binding; receptor tyrosine kinase binding; peptide hormone receptor binding
Biological process: atrioventricular canal development; brain development; cellular response to epidermal growth factor stimulus; cellular response to mechanical stimulus; cytokine-mediated signaling pathway; ephrin receptor signaling pathway; ERBB signaling pathway; face morphogenesis; fibroblast growth factor receptor signaling pathway; genitalia development; heart development; inner ear development; negative regulation of cell adhesion mediated by integrin; negative regulation of neutrophil activation; negative regulation of T cell activation; negative regulation of T cell proliferation; negative regulation of T cell receptor signaling pathway; negative regulation of type I interferon production; peptidyl-tyrosine dephosphorylation; positive regulation of D-glucose import; positive regulation of ERK1 and ERK2 cascade; positive regulation of insulin receptor signaling pathway; positive regulation of intracellular signal transduction; positive regulation of phosphatidylinositol 3-kinase/protein kinase B signal transduction; regulation of protein-containing complex assembly; and 10 more
Cellular component: cytoplasm; cytosol; focal adhesion; mitochondrion; nucleolus; nucleoplasm; nucleus; protein-containing complex
Genetic constraint (gnomAD): Loss-of-function variants: 6 observed, 75.89 expected, observed/expected ratio (o/e) 0.0791, 90% interval 0.042 to 0.16. The upper end of that interval is the gene's LOEUF score, 0.16, which puts it in group 1 of 6, group 1 being the genes least tolerant of losing a copy. Missense variants: 385 observed, 758.5 expected, observed/expected ratio (o/e) 0.51, 90% interval 0.47 to 0.55. Synonymous variants: 220 observed, 266.46 expected, observed/expected ratio (o/e) 0.83, 90% interval 0.74 to 0.92.
Gene-disease validity (ClinGen):
ClinGen rates the evidence that PTPN11 causes each of these diseases.
Noonan syndrome (autosomal dominant): Definitive. Noonan Syndrome (NS) is characterized by short stature, typical facial dysmorphism and congenital heart defects.
Noonan syndrome with multiple lentigines (autosomal dominant): Definitive. A rare multisystem genetic disorder characterized by lentigines, hypertrophic cardiomyopathy, short stature, pectus deformity, and dysmorphic facial features.
cardiofaciocutaneous syndrome (autosomal dominant): Disputed. Cardiofaciocutaneous (CFC) syndrome is a RASopathy characterized by craniofacial dysmorphology, congenital heart disease, dermatological abnormalities (most commonly hyperkeratotic skin and sparse, curly hair), growth retardation and intellectual disability.
Costello syndrome (autosomal dominant): Disputed. Costello syndrome (CS) is a rare multisystemic disorder characterized by failure to thrive, short stature, developmental delay or intellectual disability, joint laxity, soft skin, and distinctive facial features.
Cancer hallmarks: genome instability and mutations (suppresses); escaping immune response to cancer (promotes); escaping programmed cell death (suppresses); change of cellular energetics; invasion and metastasis (promotes); tumour promoting inflammation (promotes); suppression of growth (promotes); escaping programmed cell death (promotes); angiogenesis (suppresses); proliferative signalling (promotes); angiogenesis (promotes); tumour promoting inflammation (suppresses); genome instability and mutations (promotes)
Homologues: Orthologues: macaque PTPN11 (100% identical), chimpanzee PTPN11 (99% identical), dog PTPN11 (99% identical), mouse Ptpn11 (99% identical), pig PTPN11 (99% identical), rabbit PTPN11 (99% identical), rat Ptpn11 (98% identical), guinea pig PTPN11 (98% identical), chimpanzee PTPN11 (96% identical), tropical clawed frog ptpn11 (94% identical), zebrafish ptpn11a (92% identical). Paralogues in human: PTPN6 (54% identical), PTPRD (32% identical), PTPRK (32% identical), PTPRM (32% identical), PTPRF (31% identical), PTPRS (31% identical), PTPRZ1 (30% identical), PTPRT (30% identical), PTPRG (29% identical), PTPRB (28% identical), PTPRJ (27% identical), PTPRU (27% identical), and 23 more.
Diseases named in the same sentence as PTPN11 in open-access papers:
PTPN11 is named in the same sentence as 543 diseases in open-access papers, as found by Europe PMC text mining. Sharing a sentence is not in itself a finding about the gene and the disease. The quoted sentences say what the papers report.
Noonan syndrome (350 papers, 2007 to 2026). "Germline PTPN11 mutations cause developmental disorders such as Noonan Syndrome, whereas somatic mutations drive various cancers." (PMID 40631144, 2025). "Germline missense mutations in PTPN11 were found in 45% of clinically diagnosed Noonan syndrome patients." (PMID 41479460, 2025). "ASD and VSD occurred in three cases—RP40 (c.236A>G), RP70 (c.236A>G), and RP73 (c.1505C>T)—findings atypical for PTPN11-associated Noonan syndrome." (PMID 41292581, 2025). "Such glial ERK signaling drives normal synaptic pruning, and a Noonan Syndrome patient-derived protein tyrosine phosphatase non-receptor type 11 (PTPN11) mutation within glia increases ERK signaling to exacerbate experience-dependent synaptic pruning." (PMID 40040788, 2025). "Neonatal myeloproliferative disorders (MPDs) are rare conditions associated with genetic disorders such as Noonan syndrome, primarily caused by PTPN11 variants, Noonan-like syndromes or Down syndrome." (PMID 40481232, 2025). "Noonan syndrome, an autosomal dominant disorder, arises from heterozygous missense mutations in the PTPN11 gene in approximately 50% of cases." (PMID 40723369, 2025). "This amino acid change occurs within the phosphatase domain of the PTPN11 protein and is a known pathogenic variant associated with Noonan syndrome." (PMID 40282387, 2025). "Missense variants in PTPN11 disrupt SHP2’s proper catalytic activity and the regulation of signaling pathways, leading to disorders such as Noonan syndrome (NS), LEOPARD syndrome (LS), or juvenile myelomonocytic leukemia (JMML)." (PMID 41479460, 2025). "Syndromic conditions, such as Noonan syndrome (commonly due to PTPN11 and other RAS/MAPK variants), often present in infancy with short stature, facial dysmorphism, and complex valvular abnormalities alongside hypertrophy." (PMID 40868441, 2025). "Strikingly, 3 of 13 tumors exhibited pathogenic variants in Ptpn11 (encoding SHP-2) found in 50% of Noonan syndrome patients." (PMID 41223283, 2025). "Similar to other pathogenic variants in PTPN11, this mutation is associated with RASopathies, potentially including Noonan syndrome or related disorders." (PMID 40282387, 2025). "The PTPN11 gene variation identified in Noonan syndrome are known as gain-of-function mutations of the RAS/MAPK pathway." (PMID 40514730, 2025). "The predominance of PTPN11 mutations (38% of positive cases) is consistent with its known association with Noonan syndrome and its frequent implication in RASopathies globally." (PMID 41292581, 2025). "We analyzed 31 patients with clinical suspicion of Noonan syndrome and identified two individuals carrying the pathogenic PTPN11 c.922A>G variant." (PMID 41226044, 2025). "Germline mutations in the PTPN11 gene account for approximately 40% to 50% of Noonan syndrome (NS) cases, a prevalent autosomal dominant disorder marked by facial features, proportionate short stature, and heart defects." (PMID 40141849, 2025). "A RASopathy NGS panel undertaken at the referring hospital revealed presence at a heterozygous state of the c.188A>G (p.Tyr63Cys) class 5 variant of the PTPN11 gene (rs121918459), located in a hotspot and found in several subjects with Noonan syndrome." (PMID 40041314, 2025). "Animal models of Noonan syndrome caused by PTPN11 suggest reductions in astrocyte formation and axon myelination, along with promotion of neurogenesis." (PMID 41001496, 2025). "Approximately half the people with Noonan syndrome have mutations of the tyrosine-protein phosphatase non-receptor type 11 (PTPN11) gene, which is located on the long arm of chromosome 12." (PMID 38347383, 2024). "Germline mutations of PTPN11 have been identified as the most common cause of two inherited disorders, namely Noonan syndrome and Noonan syndrome with multiple lentigines (formerly known as LEOPARD syndrome)." (PMID 38510972, 2024).
Noonan syndrome (continued). "Missense mutations of PTPN11 are found in more than 50% of the Noonan syndrome cases, which is a genetic disorder resulting from hyperactivation of the Ras-MAPK pathway." (PMID 38739228, 2024). "This process is disrupted in neurons expressing PTPN11 variants associated with Rasopathies and is thought to contribute to the cognitive impairments in Noonan syndrome." (PMID 39570442, 2024). "These three patients underwent sequencing of the PTPN11 gene by gene panel for the Noonan syndrome, which led to the discovery of LoF variants in each case." (PMID 40225915, 2024). "Cases also occur in other germline disorders in which there are variants in the MAP kinase genes (e.g. Noonan’s syndrome (PTPN11) and encephalocraniocutaneous lipomatosis (FGFR1))." (PMID 39294363, 2024). "Blood was obtained from healthy subjects and from patients with Noonan syndrome with a gain-of-function mutation of PTPN11 and variable bleeding phenotype." (PMID 38236412, 2024). "Noonan syndrome, which is caused by variants in the PTPN11 gene, is associated with pulmonary valve stenosis in over 50% of children." (PMID 38339013, 2024). "Germline PTPN11 mutations underlie approximately 50% of all cases of Noonan Syndrome, a congenital disorder which is characterized by a wide range of developmental defects." (PMID 37502916, 2024). "P18 was diagnosed with Noonan syndrome after trio-WES revealed a de novo heterozygous variant of the PTPN11 gene (NM_002834.5, c.922A > G)." (PMID 39500858, 2024). "Germline gain-of-function (GoF) mutations in PTPN11, encoding SHP2, account for 50% of Noonan syndrome (NS), the most common and clinically variable among RASopathies." (PMID 38594640, 2024). "PTPN11 variants are associated to the Noonan syndrome, a well-known RASopathy characterized by short stature, facial dysmorphism, and a wide spectrum of congenital heart defects." (PMID 38459225, 2024). "Noonan syndrome (NS) is one of the most common Rasopathies, caused by mutations in PTPN11 in more than 50% of cases." (PMID 39570442, 2024). "Germline alterations included variants associated with cancer predisposition syndromes, such as CHEK2 and Noonan syndrome (PTPN11)." (PMID 39687881, 2024). "Patients with PTPN11 missense variants present clinically with Noonan Syndrome, whereas patients with PTPN11 truncating variants present with metachondromatosis—a different clinical picture." (PMID 39104744, 2024). "Conversely, gain-of-function pathogenic variants in PTPN11 are associated with distinct diseases such as the Noonan syndrome (OMIM#163950) and multiple lentigines syndrome (OMIM#151100)." (PMID 40225915, 2024). "According to literature data, the detectability of PTPN11 variants relative to all identified variants in the cohort with Noonan syndrome (NS) varies widely and ranges from 20% to 60% with a median of 36%." (PMID 38540404, 2024). "Two of these individuals have Noonan syndrome (PTPN11 and KRAS variants) and three individuals have Cardiofaciocutaneous syndrome (KRAS variants)." (PMID 37774117, 2024). "The clinical presentation of the proband was partially consistent with the PTPN11 variant, indicative of Noonan syndrome 1 (OMIM # 163950), presenting with short stature, facial dysmorphism, and a wide spectrum of congenital heart defects." (PMID 38674380, 2024). "Two of these participants have Noonan syndrome with pathogenic variants in PTPN11 (n = 1) and KRAS (n = 1)." (PMID 37774117, 2024). "On the other hand, loss of function mutations in the PTPN11 gene associate with to the Noonan syndrome with multiple lentigines (NSML) or Leopard syndrome-1 (OMIM: 151,100) without evidence for bleeding." (PMID 38236412, 2024).
Noonan syndrome (continued). "Among patients with identified causative mutations in the PTPN11 gene, 84.8% (89 cases) were diagnosed with Noonan syndrome (NS), and 15.2% (16 cases) had NSML." (PMID 38540404, 2024). "This research provides the most extensive clinical and molecular characterization of Noonan syndrome in Mexican patients, identifying 21 pathogenic variants of the PTPN11 gene." (PMID 39596579, 2024). "Germline point mutations in the PTPN11 gene lead to Noonan syndrome (NS; OMIM 163950) and LEOPARD syndrome (LS; OMIM 151100), both sharing several common features, notably skeletal abnormalities, consistent with our study cases." (PMID 39109335, 2024). "In order to search for a role of PTPN11 signaling downstream of PECAM1, we collected blood samples from six Noonan syndrome patients (N1-6), all with a gain-of-function mutation in the PTPN11 gene." (PMID 38236412, 2024). "Several previous studies have reported a correlation between rhGH treatment response and genotype in Noonan syndrome, with patients carrying the PTPN11 pathogenic variant having a poor response to rhGH treatment." (PMID 37605180, 2023). "In three patients (5.8%), WES allowed the detection of a chromosomal aneuploidy: in particular a trisomy 13, a Turner syndrome and a patient with Klinefelter syndrome and an associated PTPN11‐related Noonan syndrome (OMIM #163950)." (PMID 38041506, 2023). "Mutations in the PTPN11 gene that lead to SHP-2 hyper-activation have been identified in Noonan syndrome, juvenile myelomonocytic leukemia, myelodysplastic syndrome, B-cell acute lymphoblastic leukemia, acute myeloid leukemia, and several solid tumors." (PMID 38022587, 2023). "In CML, PTPN11 variant (NM_002834.5:c.1529A>T) p.(Gln510Leu), which is also a known variant in Noonan-syndrome (RCV001261023.1), was detected in a patient suffering from blast crisis after 10 years of TKI treatment." (PMID 37384296, 2023). "In contrast, germline mutations of PTPN11 are known to cause Noonan syndrome, a multisystem disorder characterized by abnormal facial features, developmental delay, and sporadically, also brain tumors." (PMID 36973520, 2023). "Six of the patients carried missense mutations in the PTPN11 gene, which is the most commonly mutated gene associated with Noonan syndrome (OMIM #163,950)." (PMID 37605180, 2023). "For instance, pathogenic gain-of-function mutations in the constrained PTPN11 gene (LOEUF 0.14) are a known cause of Noonan’s Syndrome." (PMID 37056996, 2023). "On the other hand, loss-of-function PTPN11 mutations give rise to an allelic disorder (Noonan’s Syndrome with Multiple Lentigines), with overlapping clinical features." (PMID 37056996, 2023). "To date, PTPN11 is the most common related genes have been reported to be associated with Noonan syndrome, which contains 15 exons and 14 introns with a full gene length of approximately 91,182 bp, and is an important signaling molecule for the cell." (PMID 37525886, 2023). "PTPN11 germline variants are present in 50% of patients suffering from Noonan-syndrome, an autosomal dominant disorder associated with heart failure and facial dysmorphia, or Leopard syndrome, a genetic disease mainly leading to heart and skin anomalies." (PMID 37384296, 2023). "This suggests that the response to rhGH treatment in Noonan syndrome patients carrying the PTPN11 gene variant is currently controversial." (PMID 37605180, 2023). "A c.417G>C variant in PTPN11 was identified in two CSFEs: one de novo and one inherited from a mother with Noonan syndrome." (PMID 36959127, 2023). "One patient, who carried a heterozygous FLNA mutation, also harbored a heterozygous PTPN11 mutation and thus presented some phenotypes of Noonan syndrome." (PMID 36830778, 2023). "In order to study the diagnosis and gene function of deafness caused by PTPN11 gene mutation syndrome, this paper first introduced the syndrome deafness, and then analyzed the PTPN11 gene and Noonan syndrome." (PMID 36760995, 2023).